ALAS1 (5'-aminolevulinate synthase 1)
Description:
Catalyzes the pyridoxal 5'-phosphate (PLP)-dependent condensation of succinyl-CoA and glycine to form aminolevulinic acid (ALA), with CoA and CO2 as by-products.
Synonyms: ALAS-H; ALAS3; ALASH; ALAS; MIG4
Tractability: Antibody: UniProt places it where antibodies can reach, with medium confidence. PROTAC: UniProt records ubiquitination sites on it; ubiquitination databases record sites on it; its protein half-life has been measured.
Gene: Protein-coding gene on chromosome 3 (52,198,086 to 52,214,585, forward strand). Ensembl gene ENSG00000023330.
Subcellular location: Mitochondrion inner membrane
Subcellular location (Human Protein Atlas): Mitochondria; Nucleoplasm
Pathways (Reactome):
Metabolism: Heme biosynthesis; PPARA activates gene expression
Metabolism of proteins: Mitochondrial protein degradation
Organelle biogenesis and maintenance: Transcriptional activation of mitochondrial biogenesis
Gene Ontology:
Molecular function: 5-aminolevulinate synthase activity; identical protein binding; protein binding; pyridoxal phosphate binding; transferase activity
Biological process: response to bile acid; heme biosynthetic process; hemoglobin biosynthetic process; cellular response to insulin stimulus; heme A biosynthetic process; heme B biosynthetic process; porphyrin-containing compound metabolic process; response to cAMP; response to cobalt ion; response to ethanol; response to gonadotropin; response to herbicide; response to hypoxia; response to nickel cation; response to nutrient levels; response to platinum ion; response to xenobiotic stimulus; tetrapyrrole biosynthetic process
Cellular component: mitochondrion; nucleoplasm; mitochondrial inner membrane; mitochondrial matrix
Genetic constraint (gnomAD): Loss-of-function variants: 29 observed, 60.92 expected, observed/expected ratio (o/e) 0.48, 90% interval 0.35 to 0.65. The upper end of that interval is the gene's LOEUF score, 0.65, which puts it in group 2 of 6, group 1 being the genes least tolerant of losing a copy. Missense variants: 672 observed, 826.72 expected, observed/expected ratio (o/e) 0.81, 90% interval 0.76 to 0.87. Synonymous variants: 292 observed, 304.78 expected, observed/expected ratio (o/e) 0.96, 90% interval 0.87 to 1.06.
Homologues: Orthologues: chimpanzee ALAS1 (100% identical), macaque ALAS1 (99% identical), dog ALAS1 (95% identical), guinea pig ALAS1 (95% identical), rabbit ALAS1 (93% identical), mouse Alas1 (92% identical), pig ALAS1 (90% identical), rat Alas1 (90% identical), tropical clawed frog alas1 (76% identical), zebrafish alas1 (71% identical). Paralogues in human: ALAS2 (56% identical), SPTLC2 (22% identical), GCAT (21% identical), SPTLC3 (20% identical), SPTLC1 (17% identical).
Diseases named in the same sentence as ALAS1 in open-access papers:
ALAS1 is named in the same sentence as 54 diseases in open-access papers, as found by Europe PMC text mining. Sharing a sentence is not in itself a finding about the gene and the disease. The quoted sentences say what the papers report.
porphyria (17 papers, 2014 to 2026). Porphyria is a group of diseases in which substances called porphyrins build up, negatively affecting the skin or nervous system. "Ketogenic and other low-carbohydrate diets increase ALAS1 activity, leading to accumulation of heme precursors and risk of acute porphyria attacks; high-carbohydrate diets and avoidance of fasting are recommended." (PMID 41486865, 2026). "Key findings included the identification of a relationship between valproic acid, ALAS1, porphyria (a disease caused by overaccumulation of porphyrin, which is essential for the function of hemoglobin), and the PPAR gene family." (PMID 37900350, 2023). "Hepatic PPARGC1A and consequently ALAS1 are upregulated by diet restriction and such a response is implicated in the precipitation of acute porphyria attacks in fasting susceptible patients." (PMID 34900592, 2021). "INH induces ALAS1 protein expression while suppressing FECH, leading to the accumulation of ALA and PPIX and thereby increasing the risk of porphyria." (PMID 40559379, 2025). "A typical treatment for porphyria involves the administration of hemin therapy or Givlaari and carbohydrates such as glucose to abate acute attacks that downregulate ALAS1." (PMID 39371821, 2024). "Only one study introducing NGS into the diagnosis of porphyria is reported, which involves the validation of a panel, including the entire coding sequences and the exon-intron junctions of the ALAS1, HMBS, CPOX, and PPOX genes." (PMID 34441276, 2021). "Fasting is known to be capable of precipitating symptoms of acute crises in porphyria as a result of the direct activation of ALAS-1." (PMID 28600349, 2017). "The episodic nature of acute porphyria symptoms is attributed to hepatic induction of ALAS1, 1 of 2 human isoforms of the gene, by endogenous and exogenous factors including dieting or fasting." (PMID 27240733, 2016). "Porphyria typically occurs in women between 20 and 30 years of age and 2–4 days prior to menstruation, as ovarian hormones, particularly progesterone, are potent inducers on ALAS1." (PMID 39090656, 2024). "Although no germline mutations in the ALAS1 gene are known to cause porphyria, ten different genes have been associated with the eight forms of porphyria." (PMID 34441276, 2021). "Importantly, whereas known inherited disorders of heme synthesis are the consequence of dominant or recessive variants of the other genes of the pathway no human porphyrias or other clinical conditions have been associated with ALAS1." (PMID 34900592, 2021). "Finally, this may be coupled with an infusion of hemin, the only specific treatment for porphyria designed to expand the intracellular regulatory heme pool, activating the feedback inhibition of ALAS1 activity and subsequently reducing the production of ALA and its metabolites." (PMID 39597922, 2024). "Givosiran (siRNA) is an emerging AIP therapy capable of silencing delta-aminolevulinic acid synthase-1 (ALAS1) and, in turn, reducing the accumulation of delta-aminolevulinic acid (ALA) and porphobilinogen (PBG) that precede porphyria symptoms." (PMID 39597922, 2024). "This is supported by the recent siRNA knockdown of the ALAS1 mRNA showing effective prevention of adverse effects from acute hepatic porphyrias, pointing to a similar therapeutic benefit of ALAS2 inhibition for porphyrias in the erythropoietic pathway." (PMID 32499479, 2020).
Acute hepatic porphyria (10 papers, 2020 to 2025). Acute hepatic porphyrias represent a sub-group of porphyrias (see this term) characterized by the occurrence of neuro-visceral attacks with or without cutaneous manifestations. "Givosiran is designed to inhibit hepatic 5-aminolevulinic acid synthase 1 (ALAS1) to treat acute hepatic porphyria caused by disruption of ALAS1 expression, which can result in accumulation of toxic metabolites." (PMID 39967915, 2023). "Givosiran, developed by Alnylam, targets 5′-aminolevulinate synthase 1 (ALAS1) for the treatment of acute hepatic porphyria and received FDA approval in November 2019." (PMID 40149911, 2025). "In the clinical practice, givosiran, an RNAi therapeutic drug by targeting aminolevulinic acid synthase 1 (ALAS1) has been developed for the treatment of acute hepatic porphyria (AHP)." (PMID 38991028, 2024). "For example, givosiran is a GalNAc-conjugated siRNA therapeutic agent targeting 5′-aminolevulinate synthase 1 (ALAS1) that is approved for the treatment of acute hepatic porphyria (AHP) in the United States and in the European Union." (PMID 36835426, 2023). "Givosiran inhibits hepatic synthesis of delta aminolevulinate synthase 1 (ALAS1) in patients with acute hepatic porphyria (AHP), which is a rare inherited disease of haem biosynthesis." (PMID 33821570, 2021). "Acute hepatic porphyria (AHP) is a genetic disorder in which the enzyme delta-aminolevulinate synthase 1 (ALAS1) is produced in excess." (PMID 32604776, 2020). "Furthermore, the method can be used to monitor the in vivo expression patterns in patients under mRNA altering therapies like gene specific silencing RNAs (for example givosiran against ALAS1 in the acute hepatic porphyrias) or splice modulating oligos directed against FECH c.[315-48C]." (PMID 35923227, 2022). "It is used in the treatment of acute hepatic porphyria (AHP) and acts by degrading 5-aminolevulinic acid synthase 1 (ALAS1) mRNA, resulting in reduced levels of intermediates associated with AHP attacks." (PMID 35890248, 2022).
Insulin resistance (7 papers, 2018 to 2025). Increased resistance towards insulin, that is, diminished effectiveness of insulin in reducing blood glucose levels. "ALAS1-heterozygous (ALAS1+/−) mice develop metabolic dysfunction characterized by insulin resistance, glucose intolerance, and abnormal glycogen accumulation, linked mechanistically to reduced AMP-activated protein kinase (AMPK) signaling." (PMID 40868906, 2025). "Here, we showed that Alas1+/− mice displayed insulin resistance, which was cured by 5-ALA administration." (PMID 34576181, 2021). "In another ALAS1 knockout model, aged mice show some symptoms of impaired glucose tolerance and insulin resistance with evidence of skeletal muscle mitochondrial attenuation." (PMID 34900592, 2021). "In this study, we demonstrate that A1+/-s develop impaired glucose tolerance, insulin resistance and an attenuation of mitochondrial function in skeletal muscle beyond 15 wks of age, correlating with the reduced expression of ALAS1." (PMID 29364890, 2018). "These aging phenotypes, sarcopenia, insulin resistance, and mitochondrial dysfunction, parallel those of our ALAS1+/− mice described in Section 3 and Section 4 and may reflect cumulative consequences of heme insufficiency over time with aging." (PMID 40868906, 2025). "It has been suggested that insulin resistance might reduce glycine level by inducing δ-aminolevulinic acid synthase 1 (ALAS1) that produces 5-aminolevulinic acid from glycine." (PMID 33664666, 2020). "Furthermore, it's worth noting that animals with a single functional copy of the ALAS1 gene (ALAS1 heterozygous mice) exhibit a prediabetic phenotype when maintained under normal feeding conditions, along with the development of age-dependent glucose intolerance and insulin resistance." (PMID 38581583, 2024). "Mice heterozygous null for ALAS1 (A1+/-s) experience impaired glucose tolerance (IGT) and insulin resistance (IR) beyond 20-weeks of age (aged A1+/-s)." (PMID 29364890, 2018). "Despite showing no phenotypical changes when young, ALAS1+/− mice older than ~20–25 weeks develop impaired glucose tolerance and insulin resistance without obesity." (PMID 40868906, 2025). "They further found that 5-ALA deficiency resulted in heme deficiency because of decreased glucose uptake in myocytes of mice with absent ALAS1 or those with a block in heme synthesis, ultimately suggesting that ALA deficiency in vivo can lead to impaired glucose levels and insulin resistance." (PMID 31781665, 2019).
acute intermittent porphyria (5 papers, 2002 to 2023). Acute intermittent porphyria is the most frequent and the most severe form of the acute hepatic porphyrias. "The management of a patient with acute intermittent porphyria typically starts with termination of potential causative medications and intravenous administration of glucose (300–400 g/24 h), which inhibits transcription of the gene encoding transhepatic 5’-aminolevulinate synthase 1 (ALAS1)." (PMID 36346432, 2023). "Givosiran is another example of the developed RNAi based therapeutic agent loaded in lipid NPs to reduce the expression of delta aminolevulinic acid synthase 1 (ALAS1) gene and hence treating acute Intermittent porphyria (AIP)." (PMID 38047291, 2023). "Acute intermittent porphyria (AIP) is characterized by acute neurovisceral attacks that are precipitated by the induction of hepatic 5-aminolevulinic acid synthase 1 (ALAS1)." (PMID 38254627, 2023).
diabetes (4 papers, 2016 to 2024). "Although these findings were limited to a single study, they appear particularly intriguing when considering the link between diabetes and ALAS1-catalysed heme synthesis." (PMID 38581583, 2024). "However, the recently proposed role of FLVCR1a as a choline importer introduces novel perspectives and implies that, in conjunction with the regulation of ALAS1 and heme biosynthesis, FLVCR1a's involvement in both diabetes and cancer may also hinge on choline-related mechanisms." (PMID 38581583, 2024). "We observed that the addition of cDDGS positively affects the expression of several genes that have been recently proposed as potential targets for the treatment of obesity, diabetes, cardiovascular disease, and Alzheimer’s disease (e.g., FASN, AACS, ALAS1, HMGCS1, and VSIG4)." (PMID 30509175, 2018).
lung cancer (4 papers, 2013 to 2021). A malignant neoplasm involving the lung. "As demonstrated by studies performed recently, ALAS1 can affect many cellular functions and has important effects on non–small cell lung cancer, colorectal cancer and oral cancer." (PMID 33300278, 2021). "While we do not have much evidence about Ftmt in cancer, there are some studies about ALAS1 in lung cancer." (PMID 28166223, 2017). "Although its transcript level is detected in lung cancer cells, its level appears to be significantly lower compared to that of ALAS1." (PMID 23704904, 2013).
non-small cell lung carcinoma (4 papers, 2017 to 2023). A group of at least three distinct histological types of lung cancer, including non-small cell squamous cell carcinoma, adenocarcinoma, and large cell carcinoma. "It was found that ALAS1 protein levels were substantially increased in non-small-cell lung cancer cells compared to normal cells." (PMID 28166223, 2017). "Nonspecific 5-aminolevulinate synthase (ALAS1) is another interesting protein, already associated with the development of various types of cancer, such as non-small-cell lung cancer and colorectal neoplasms." (PMID 37046807, 2023). "As for ALAS gene, in non-small-cell lung cancer, non-erythrocyte ALAS1 gene transcription levels and ALAS1 protein levels were significantly elevated in cancer cells, while ALAS2 transcription levels were increased nearly 5-fold in HCC4017 cells." (PMID 33042807, 2020).
acute porphyria (3 papers, 2016 to 2024). "ALAS1 encodes the mitochondrial enzyme that catalyzes the rate-limiting step in heme biosynthesis and is associated with acute porphyria and sideroblastic anemia." (PMID 35207686, 2022).
colorectal cancer (3 papers, 2021 to 2023). A primary or metastatic malignant neoplasm that affects the colon or rectum. "Zhao39 found that silencing the expression of ALAS1 could inhibit the proliferative and metastatic abilities of colorectal cancer cells." (PMID 35651292, 2023).
Glucose intolerance (3 papers, 2023 to 2025). Glucose intolerance (GI) can be defined as dysglycemia that comprises both prediabetes and diabetes. "Alas1 is associated with glucose intolerance in skeletal muscle and Hipk2 is associated with cell proliferation and inflammation in skeletal muscle." (PMID 37012297, 2023).
Alzheimer disease (2 papers, 2018 to 2025). A progressive, neurodegenerative disease characterized by loss of function and death of nerve cells in several areas of the brain leading to loss of cognitive function such as memory and language. "For instance, key enzymes in the heme biosynthesis pathway, 5-aminolevulinate synthase 1 (ALAS1) and PBGD, were found to be reduced in Alzheimer’s disease (AD) patients." (PMID 41157189, 2025).
iron deficiency (2 papers, 2018). "In cellular iron deficiency, IRPs bind to IREs at the 5’ untranslated region (UTR) of FPN1, FtH, FtL, delta-aminolevulinate synthase 1 (ALAS1), aconitase 2 (ACO2), hypoxia-inducible factor 2 (HIF2) mRNAs to mediate the degradation of the transcripts of the IREs to decrease iron storage and export." (PMID 30558109, 2018).
acute myeloid leukemia (1 paper, 2023). Acute myeloid leukemia (AML) is a group of neoplasms arising from precursor cells committed to the myeloid cell-line differentiation. "ALAS1, the rate limiting step of heme biosynthesis, has previously been identified as a ClpP substrate and loss of heme biosynthesis has been implicated as a metabolic vulnerability in acute myeloid leukemia." (PMID 37063293, 2023).
asthma (1 paper, 2026). "Multi-omics integration associated ALAS1 (cg13241645, cg15698299) and TXNRD1 (cg09884423) with asthma at both methylation and expression levels, with colocalization supporting both ALAS1 associations." (PMID 41896191, 2026). "This study provides multi-omics evidence supporting a causal role for mitochondrial-related genes, particularly ALAS1 and TXNRD1, in paediatric asthma, offering new insights into pathogenesis and potential therapeutic targets." (PMID 41896191, 2026).
congenital sideroblastic anaemia (1 paper, 2015). "Therefore, we prepared CD34+ BM cells from four SF3B1-mutated MDS-RS patients (MDS1, TP1; MDS2, TP1; MDS3; MDS4) and one congenital sideroblastic anaemia patient (MDS5 with ALAS1 mutation), which was used as a control." (PMID 26643973, 2015).
coronary artery disease (1 paper, 2022). "Alas1, as a rate-limiting enzyme for heme biosynthesis in the mitochondrial matrix, was associated with coronary artery disease." (PMID 36712272, 2022).
endometrial cancer (1 paper, 2023). Primary or metastatic malignant neoplasm involving the endometrium (mucous membrane that lines the endometrial cavity). "Further analysis showed that estrogen and succinate increased the expression of ALAS1 and SLC25A38 in uterine endometrial cancer cells (UECC), and the administration of succinate upregulated the level of the estrogen receptor (ER)." (PMID 37509133, 2023).
hepatocellular carcinoma (1 paper, 2023). A malignant tumor that arises from hepatocytes. "Some of the genes in these pathways include ALAS1, ACAA1, and ACOX2 which are negatively correlated with recurrence-free survival in patients with hepatitis B-related (HBV) hepatocellular carcinoma (HCC)." (PMID 36768794, 2023).
laryngeal carcinoma (1 paper, 2023). Carcinoma that arises from the laryngeal epithelium. "We suggest that the combination of ALAS1+RPL29 reference genes is best for normalization of target gene expression in laryngeal cancer and/or normal tissue samples." (PMID 38031942, 2023).
liver cancer (1 paper, 2024). An epithelial or non-epithelial malignant neoplasm that arises from the liver. "Among heme biosynthesis enzymes, only the first two-step genes ALAS1 and ALAD were downregulated in liver cancer lines." (PMID 39199347, 2024).
liver disease (1 paper, 2023). "For instance, QotM #1 focused on an unexpected observation that valproic acid reversibly induces ALAS1, a gene that encodes a mitochondrial enzyme involved with heme or iron protoporphyrin biosynthesis, in models of liver disease or injury." (PMID 37900350, 2023).
liver fibrosis (1 paper, 2021). "Conversely, hemin directly represses ALAS1 activity, but its long-term exposure has been associated with hepatic iron accumulation, oxidative stress, inflammation, and liver fibrosis in AIP patients alongside refractoriness to the attacks, growing the need of novel medications." (PMID 34573969, 2021).
melanoma (1 paper, 2025). A malignant, usually aggressive tumor composed of atypical, neoplastic melanocytes. "Notable findings include NRAS Q61L melanomas being enriched for modules involving C19orf10 and ARF4, while BRAF V600E melanomas were enriched for modules involving ALAS1 and MYO1B." (PMID 39796775, 2025).
ovarian carcinoma (1 paper, 2023). A malignant neoplasm originating from the surface ovarian epithelium. "The expression of ALAS2, HMBS, and FXN involved in iron utilization was associated with improved OS in ovarian cancer, whereas the expression of ALAD, ALAS1, and CPOX in this process was associated with poor OS in ovarian cancer." (PMID 38186569, 2023).